KCNJ5 (potassium inwardly rectifying channel subfamily J member 5)
Description:
Inward rectifier potassium channels are characterized by a greater tendency to allow potassium to flow into the cell rather than out of it. Their voltage dependence is regulated by the concentration of extracellular potassium; as external potassium is raised, the voltage range of the channel opening shifts to more positive voltages. The inward rectification is mainly due to the blockage of outward current by internal magnesium. Can be blocked by external barium. This potassium channel is controlled by G proteins.
Synonyms: CIR; GIRK4; Kir3.4; KATP1; LQT13
Tractability: Small molecule: an approved drug acts on it; a high-quality ligand is known; it belongs to a druggable protein family. Antibody: its Gene Ontology location is reachable by antibodies, with high confidence; UniProt predicts a signal peptide or a membrane-spanning region. PROTAC: a small molecule that binds it is known.
Target class: Inwardly rectifying potassium channel; Potassium channels; Voltage-gated ion channel; Ion channel
Gene: Protein-coding gene on chromosome 11 (128,890,453 to 128,921,163, forward strand). Ensembl gene ENSG00000120457.
Subcellular location: Membrane
Pathways (Reactome):
Neuronal System: Activation of G protein gated Potassium channels; Inhibition of voltage gated Ca2+ channels via Gbeta/gamma subunits
Gene Ontology:
Molecular function: G-protein activated inward rectifier potassium channel activity; inward rectifier potassium channel activity; protein binding; voltage-gated potassium channel activity involved in atrial cardiac muscle cell action potential repolarization; voltage-gated potassium channel activity involved in ventricular cardiac muscle cell action potential repolarization
Biological process: membrane repolarization during atrial cardiac muscle cell action potential; potassium ion import across plasma membrane; regulation of heart rate by cardiac conduction; potassium ion transmembrane transport; potassium ion transport; ventricular cardiac muscle cell membrane repolarization; membrane repolarization during ventricular cardiac muscle cell action potential
Cellular component: membrane; voltage-gated potassium channel complex; plasma membrane; inward rectifier potassium channel complex
Genetic constraint (gnomAD): Loss-of-function variants: 12 observed, 21.33 expected, observed/expected ratio (o/e) 0.56, 90% interval 0.36 to 0.91. The upper end of that interval is the gene's LOEUF score, 0.91, which puts it in group 3 of 6, group 1 being the genes least tolerant of losing a copy. Missense variants: 446 observed, 579.34 expected, observed/expected ratio (o/e) 0.77, 90% interval 0.71 to 0.83. Synonymous variants: 210 observed, 223.13 expected, observed/expected ratio (o/e) 0.94, 90% interval 0.84 to 1.05.
Gene-disease validity (ClinGen):
ClinGen rates the evidence that KCNJ5 causes each of these diseases.
familial hyperaldosteronism type III (autosomal dominant): Definitive. Familial hyperaldosteronism type III (FH-III) is a rare heritable form of primary aldosteronism (PA) that is characterized by early-onset severe hypertension, non glucocorticoid-remediable hyperaldosteronism, overproduction of 18-oxocortisol and 18-hydroxycortisol, and profound hypokalemia.
long QT syndrome (autosomal dominant): Disputed.
Homologues: Orthologues: chimpanzee KCNJ5 (99% identical), macaque KCNJ5 (97% identical), pig KCNJ5 (96% identical), rabbit KCNJ5 (95% identical), mouse Kcnj5 (94% identical), rat Kcnj5 (94% identical), guinea pig KCNJ5 (93% identical), tropical clawed frog kcnj5 (74% identical), zebrafish kcnj5 (73% identical). Paralogues in human: KCNJ6 (71% identical), KCNJ9 (61% identical), KCNJ3 (53% identical), KCNJ2 (46% identical), KCNJ12 (46% identical), KCNJ18 (45% identical), KCNJ4 (44% identical), KCNJ14 (43% identical), KCNJ8 (39% identical), KCNJ11 (38% identical), KCNJ1 (37% identical), KCNJ10 (32% identical), and 3 more.
Diseases named in the same sentence as KCNJ5 in open-access papers:
KCNJ5 is named in the same sentence as 86 diseases in open-access papers, as found by Europe PMC text mining. Sharing a sentence is not in itself a finding about the gene and the disease. The quoted sentences say what the papers report.
adenoma (63 papers, 2012 to 2025). A neoplasm arising from the epithelium. "The most typical presentation of a clear-cut unilateral adenoma causing PA (Conn’s syndrome) is more likely in people with the somatic KCNJ5 mutation." (PMID 41066498, 2025). "KCNJ5 mutations, in particular, are linked to better post-adrenalectomy outcomes often with more complete hypertension remission due to distinct adenoma features." (PMID 41438295, 2025). "Women with aldosterone-producing adenomas have a higher prevalence of somatic KCNJ5 mutations than men, and patients harbouring these mutations are likely to have more favourable clinical outcomes after adrenalectomy." (PMID 40296186, 2025). "Several studies have found that patients with KCNJ5-mutated tumours are typically younger, have a lower potassium level, a higher aldosterone level, and larger adenomas." (PMID 40725432, 2025). "In a recent paper investigating potassium inwardly rectifying channel subfamily J member 5 (KCNJ5)-mutated aldosterone-producing adenomas, p21-induced cell cycle arrest was correlated with higher aldosterone-to-renin ratios." (PMID 38500373, 2024). "The glycine-to-arginine and leucine-to-arginine substitutions at positions 151 (G151R) and 168 (L168R), respectively, account for the majority of KCNJ5 mutations in aldosterone-producing adenomas." (PMID 39765659, 2024). "In KCNJ5-mutated and wild-type aldosterone-producing adenomas, compact tumor cells were more likely to be senescent than intratumor clear cells." (PMID 38500373, 2024). "Aldosterone-producing adenomas with somatic KCNJ5 mutations have been found to exhibit unique molecular characteristics including global DNA hypomethylation and transcriptomic profiles with gene expression changes." (PMID 39765659, 2024). "The observed pathological variants of aldosterone-producing adenomas in our cohort were KCNJ5 (N=5), ATP1A1 (N=5), and CACNA1D (N=4) mutations." (PMID 39897961, 2024). "KCNJ5 mutated adenomas account for the large majority of the cases (~ 40% of aldosterone-producing adenomas) and tend to mainly affect young female patients." (PMID 38108848, 2024). "PubMed literature research using keywords combination, including “aldosterone-producing adenoma,” “somatic mutations,” “KCNJ5,” “organ damage,” “cardiovascular,” “diastolic function,” “metabolic syndrome,” “autonomous cortisol secretion,” etc." (PMID 36950676, 2023). "A previous study reported upregulated BEX1 gene expression in APAs with a CACNA1D or ATP1A1 mutation (that tend to be small adenomas) compared with the larger KCNJ5-mutated APAs." (PMID 36004349, 2022). "KCNJ5 mutations are highly prevalent in APAs, associated with larger adenoma size, female sex, and more severe aldosteronism." (PMID 36004349, 2022). "We present here a novel somatic KCNJ5 p.I157S mutation in an aldosterone-producing adenoma from a 16-year-old black female whose severe drug-resistant hypertension significantly improved following unilateral adrenalectomy." (PMID 36051386, 2022). "Only a limited number of cases of aldosterone-producing adenomas with somatic KCNJ5 gene mutations have been described in children." (PMID 36051386, 2022). "In the present study, we identified a somatic mutation of KCNJ5 157-159delITE in our tissue bank of unilateral aldosterone-producing adenomas." (PMID 34440230, 2021). "The patient harboring somatic KCNJ5 157-159delITE mutation showed positive staining for CYP11B2 in her adenoma and in an aldosterone-producing micronodule in the adjacent adrenal tissue." (PMID 34440230, 2021). "Our result showed no immunoreactivity of CYP11B1 and weak immunoreactivity of CYP17A1 presented in this KCNJ5 157-159delITE mutated adenoma." (PMID 34440230, 2021). "Sanger sequencing of DNA extracted from tissue slices revealed that both left and right adenomas carried the same aldosterone-driver KCNJ5 gene mutation, but with different nucleotide changes." (PMID 34630330, 2021).
adenoma (continued). "The absence of trophic effects of the KCNJ5 mutations suggests that APA cells bearing KCNJ5 mutations essentially require an additional factor or mutation to cause adenoma formation." (PMID 34681640, 2021). "Plasma steroid profiles varied according to disease subtype and were particularly distinctive in patients with adenomas due to KCNJ5 variants, who showed better rates of biochemical cure after adrenalectomy than other patients." (PMID 32990741, 2020). "In contrast, the steroid profile alone showed superior performance over the aldosterone to renin ratio for identifying unilateral disease, particularly adenomas due to KCNJ5 variants." (PMID 32990741, 2020). "Several somatic mutations have been found in aldosterone-producing adenomas in KCNJ5, ATP1A1, ATP2B3, CACNA1D, and CTNNB1 genes." (PMID 32783015, 2020). "Mutations in KCNJ5 (potassium channel) have been documented in patients with aldosterone-producing adenomas in approximately 40% of patients from European cohorts, though much higher rates are reported in patients from Japan and Asia." (PMID 32266384, 2020). "KCNJ5 mutations were identified in approximately 40–50% (range, 30.2–76.8%) of aldosterone-producing adenomas." (PMID 29594118, 2018). "In the majority of aldosterone-producing adenomas, somatic driver mutations in the KCNJ5, ATP1A1, ATP2B3, CACNA1D, and CTNNB1 genes have been identified." (PMID 28422753, 2017). "APA carrying KCNJ5 mutations account for nearly 40% of sporadic adenomas, a frequency that increases to 73% in populations from East Asia." (PMID 28420172, 2017). "The results of mRNA expression from real-time PCR showed that CTNNB1 mutated adenoma had similar density of CYP11B2 expression as WT patients; however, both groups of adenoma had less CYP11B2 expression than those with KCNJ5 mutations (all p < 0.01)." (PMID 28102204, 2017). "The aim of this study was to show the effect of KCNJ5 mutational status on arterial stiffness in aldosterone-producing adenomas after adrenalectomy." (PMID 28415786, 2017). "The CTNNB1 mutants displayed higher, diffuse active β–catenin expression than KCNJ5 mutation carriers or WT, especially in adenomas from female patients; and showed prominent nuclear staining." (PMID 28102204, 2017). "Na+-permeable gain-of-function mutations of KCNJ5 are causative for some 40 % of aldosterone-producing adenomas." (PMID 25339223, 2015). "In all 137 cases in which matched DNA from blood or surrounding normal tissue was available, KCNJ5 mutations were specific to adenomas, consistent with these representing somatic mutations." (PMID 22848660, 2012). "KCNJ5 mutations were overrepresented in aldosterone producing adenomas from female compared to male patients (63 vs. 24%)." (PMID 22848660, 2012). "This discrepancy could be explained by the high prevalence of adenoma related to KCNJ5 mutation in Japan, a mutation that is more frequent in women than in men." (PMID 40838514, 2025). "Almost 50% of adenomas (n=10) carried a KCNJ5 mutation, of which 90% (n=9) were female." (PMID 39678193, 2024). "Pathogenic variants in the KCNJ5 were detected in the adenoma." (PMID 39027636, 2024). "However, restricting analysis to adenomas with either a KCNJ5 or a CACNA1D mutation classified these 2 genotype groups with significant differences of 137 metabolites." (PMID 36004349, 2022). "Thus, we concluded that the immunohistological data implicated that the adenoma harboring KCNJ5 157-159delITE mutation affected the aldosterone production." (PMID 34440230, 2021). "The results above could be also explained by the fact that KCNJ5-mutated APAs had higher hormonal activity compared to WTs and WT adenomas had more abundant compact cells structure." (PMID 34070051, 2021).
adenoma (continued). "This revealed markedly elevated levels of 18-oxocortisol, 18-hydroxycortisol, 11-deoxycorticosterone, and 11-deoxycortisol, a steroid profile that strongly suggested that the left sided adrenal mass was an aldosterone producing adenoma, most likely due to a somatic KCNJ5 mutation." (PMID 31555214, 2019). "Interestingly, although germline mutations in KCNJ5 are rare, somatic mutations of KCNJ5 have been described in nearly half of aldosterone-producing adenomas." (PMID 29439489, 2018). "Aldosterone-producing adenomas frequently carry a causative somatic mutation in either of a number of genes with the KCNJ5 gene, encoding an inwardly rectifying potassium channel, a recurrent target harboring mutations at a prevalence of more than 40% worldwide." (PMID 29642543, 2018). "Aldosterone and glucocorticoid co-secreting adenomas have been reported to harbor KCNJ5 mutations." (PMID 29594118, 2018). "The generalized additive model smoothing plot showed that aldosterone-producing adenoma patients who carried the KCNJ5 mutation and were aged between 37 and 60 may have a hypertension recovery advantage." (PMID 28415786, 2017). "Summary of reported KCNJ5 somatic mutations in Aldosterone producing adenomas." (PMID 22848660, 2012). "Machine learning–designed combinatorial plasma steroid profiles may facilitate both screening for primary aldosteronism and identification of patients with unilateral adenomas due to pathogenic KCNJ5 variants, who are most likely to show benefit from surgical intervention." (PMID 32990741, 2020). "This diagnostic study assesses whether plasma steroid profiling combined with machine learning facilitates diagnosis and treatment stratification of patients with primary aldosteronism, particularly those with unilateral adenomas due to pathogenic KCNJ5 sequence variants." (PMID 32990741, 2020). "It has been suggested that selective inhibitors of mutant KCNJ5 channels have the potential to improve this situation: a drop in blood pressure and/or aldosterone upon administration of such inhibitors could allow for the noninvasive identification of patients with adenomas carrying KCNJ5 mutations." (PMID 31695023, 2019). "Yet, the average adenoma size, based on the diameter, was significantly larger in KCNJ5 mutant APAs compared to non-KCNJ5-mutant adenomas (13 ± 0.8 vs. 9 ± 0.9; p = 0.001)." (PMID 40557039, 2025). "Within T-DNA, somatic variants were identified in 53% of adenomas: PRKACA in 2/7 CPA-CS, CTNNB1 in 3/5 CPA-MACS and 1/7 CPA-CS, KCNJ5 in 2/5 APA and CACNA1D in 1/5 APA." (PMID 39891827, 2025). "Adenomas with CTNNB1 mutations showed a large number of differentially expressed genes (1360 compared to 106 and 75 for KCNJ5 and ATP1A1/ATP2B3 respectively) and clustered together in a hierarchical clustering analysis." (PMID 31000732, 2019). "Several studies reported that KCNJ5-mutant aldosterone-producing adenomas are associated with younger age, female gender, and larger tumor size than KCNJ5-wild-type aldosterone-producing adenomas." (PMID 29594118, 2018). "At the molecular level, somatic mutations involving potassium channels (KCNJ5), ATPases (ATP1A1 and ATP2B3), and calcium channels (CACNA1D) account for approximately 60% of sporadic aldosterone-producing adenomas." (PMID 29594118, 2018). "In contrast, KCNJ5-wild-type adenomas were reported to be more common in older men and smaller in size." (PMID 29594118, 2018). "The lack of somatic KCNJ5 mutations in unilateral hyperplasia and in the paradoxical ZG hyperplasia surrounding KCNJ5-mutant aldosterone-producing adenomas is of significance." (PMID 29594118, 2018). "Several lines of evidence suggest that KCNJ5-mutant aldosterone-producing adenomas have distinct clinicopathological phenotype compared to those harboring ATP1A1, ATP2B3, and CACNA1D mutations." (PMID 29594118, 2018). "Targeted sequencing for the reported mutations in APAs of KCNJ5, CACNA1D, ATP1A1, ATP2B3 and CTNNB1 exons was performed from the adenomas." (PMID 28102204, 2017).
adenoma (continued). "CYP11B2 expressed diffusely on adenomas harboring CTNNB1 mutations and showed mottled staining on adenomas harboring KCNJ5 mutations." (PMID 28102204, 2017). "NEFM, a gene highly upregulated in zona glomerulosa, was upregulated in KCNJ5 wild-type aldosterone-producing adenomas." (PMID 27777363, 2016). "NR4A2, the transcription factor for aldosterone synthase, was highly expressed in zona fasciculata adjacent to a KCNJ5-mutant aldosterone-producing adenoma." (PMID 27777363, 2016). "ACSS3, encoding the enzyme that synthesizes acetyl-CoA, was the top gene upregulated in KCNJ5-mutant aldosterone-producing adenoma compared with wild-type." (PMID 27777363, 2016). "Multiple regression analysis revealed that the presence of the KCNJ5 mutation was negatively linked to GNRHR mRNA expression levels following adjustment for gender, age, serum potassium levels, and adenoma diameter." (PMID 27196470, 2016). "Comparing KCNJ5-mutant aldosterone-producing adenoma, zona glomerulosa, and zona fasciculata samples with wild-type samples, 138, 56, and 59 genes were differentially expressed, respectively (fold-change >2; P<0.05)." (PMID 27777363, 2016). "Recently, either of two recurrent somatic missense mutations (G151R or L168R) was found in the potassium channel KCNJ5 gene in aldosterone producing adenomas." (PMID 22848660, 2012). "KCNJ5 staining using specific antibodies were variable in both adenomas and adenoma-like macronodules, showing intense, weak or heterogenous staining." (PMID 22848660, 2012). "Furthermore, somatic mutations in other genes, such as KCNJ5, CACNA1D, and ATP1A1, have been implicated in aldosterone-producing adenomas, highlighting the complex genetic landscape of adrenal tumors." (PMID 41007858, 2025). "Furthermore, a large proportion of patients with UPA likely has KCNJ5 sequence variations, the most common sequence variation in aldosterone-producing adenomas in China and Japan, and these patients tend to achieve biochemical and clinical cure." (PMID 37870836, 2023). "The heterogeneity of the tumor cell compositions of aldosterone- and cortisol-producing adenoma (A/CPA) and somatic mutation of KCNJ5 may have led to different hormone secretions in the bilateral adrenal adenomas." (PMID 36960396, 2023). "In the last decade, somatic pathogenic variants in KCNJ5, CACNA1D, ATP1A1 and ATP2B3 genes, which are involved in maintaining intracellular ionic homeostasis and cell membrane potential, were described in aldosterone-producing adenomas (aldosteronomas)." (PMID 35813615, 2022). "In case 13, two nodules with clear borders that were similar to adenomas neither expressed CYP11B2 nor harbored KCNJ5 mutations." (PMID 35492351, 2022). "In the APA harboring KCNJ5 157-159delITE mutation, the immunohistochemistry (IHC) analysis showed a strong immunoreactivity and heterogenous expression for aldosterone synthase (CYP11B2) within that adenoma." (PMID 34440230, 2021). "Moreover, we have used Sanger sequencing to confirm that there were no other conventional and well-characterized aldosterone-driving gene mutations, including KCNJ5, ATP1A1, CACNA1D, and CTNNB1, in the adenoma harboring with ATP2B3 K416_F418delinsN mutation." (PMID 34572956, 2021). "Adenomas with KCNJ5 mutations tend to be larger than those which do not carry the mutation and appear to be more common in women than men." (PMID 32266384, 2020). "Primary aldosteronism was confirmed in 273 patients (165 men [60%]; mean [SD] age, 51 years), including 134 with bilateral disease and 139 with unilateral adenomas (58 with and 81 without somatic KCNJ5 sequence variants)." (PMID 32990741, 2020). "This gene encodes a voltage-gated calcium channel and 11% of aldosterone-producing adenomas without mutations in KCNJ5 have been reported to carry mutations in this gene." (PMID 32266384, 2020). "Furthermore, KCNJ5-mutant aldosterone-producing adenomas tend to be either solitary tumors or dominant tumors." (PMID 29594118, 2018).